RIPK3 (receptor interacting serine/threonine kinase 3)
Diseases named in the same sentence as RIPK3 in open-access papers (continued):
Sharing a sentence is not in itself a finding about the gene and the disease.
aortic aneurysm (3 papers, 2020 to 2022). A ruptured aneurysm located in the wall of the proximal portion of the descending aorta proceeding from the arch of the aorta. "The current study investigated the signaling steps downstream of RIPK3 in the context of aortic aneurysm." (PMID 34572045, 2021). "In 2015, our lab investigated the hypothesis that RIPK3 mediated necroptosis, not just apoptosis, is involved in aortic aneurysm pathogenesis." (PMID 33142926, 2020).
brain injuries (3 papers, 2021 to 2024). "One study revealed that PEBP1 acts as a switch between ferroptosis and necroptosis by inhibiting pro-necroptotic RIPK3 activity while activating 15-LOX to produce pro-ferroptotic HpETE-PE signals after irradiation and brain trauma." (PMID 39286656, 2024).
cholestasis (3 papers, 2019 to 2023). Impairment of the bile flow caused by obstruction within the liver, or outside the liver in the bile duct system. "In chronic liver diseases associated with cholestasis, induction of RIPK3 expression may be an early event signaling danger and repair through releasing IL-8." (PMID 37072399, 2023). "Hydrophobic TCDCA also frequently increased during cholestasis, reducing the expression and phosphorylation of RIPK3." (PMID 37072399, 2023). "In diseases leading to cholestasis, the RIPK3 expression is induced in mice and humans in a cell-type-specific manner." (PMID 37072399, 2023). "In the hepatocytes, the RIPK3 fluorescent intensity (FI) was significantly increased the cholestasis group." (PMID 37072399, 2023). "To compare whether RIPK3 expression can also be induced in patients with a cholestatic liver injury, we compared the hepatic RIPK3 expression in patients with elevated bilirubin levels, thus cholestasis." (PMID 37072399, 2023). "Findings based on BDL of the mouse models suggested a positive correlation between the expression of RIPK3 and MLKL and liver injury; moreover, knockout of RIPK3 could improve cholestasis-related inflammatory necrosis, which was especially effective soon after BDL." (PMID 35432812, 2021). "However, hepatocellular RIPK3 expression was significantly higher in patients with cholestasis than those without clinically diagnosed cholestasis." (PMID 37072399, 2023).
cognitive decline (3 papers, 2023 to 2025). "Moreover, inhibition of RIPK3 can inhibit Aβ accumulation and neuronal loss suggesting that these strategies can protect neurons and inhibit amyloid pathology in hyperthyroidism-induced cognitive decline." (PMID 37740205, 2023). "Interventions inhibiting key necroptosis molecules such as RIPK1, RIPK3, and MLKL may hold promise for mitigating AD-related pathology and cognitive decline." (PMID 40161268, 2025).
colorectal tumor (3 papers, 2016 to 2025). "The low expression of RIPK3 in human colorectal tumors was found to be associated with poor disease-free survival and overall survival." (PMID 36077828, 2022). "Functional roles of RIPK3 in CRC were confirmed in inflammation-associated and sporadic murine colorectal tumor models, as RIPK3 deficiency significantly aggravated tumor burden in both models." (PMID 36077828, 2022). "Necroptosis in tumor cells appears to be a favorable factor for colorectal tumor clearance, as downregulation of several of the key molecules in necroptotic signaling, such as RIPK3 and MLKL, are related to poor prognosis in CRC." (PMID 36077828, 2022). "In contrast to these studies, a recently published study reported that RIPK3 deficiency or MLKL deficiency had no impact on inflammation-associated or sporadic colorectal tumor development in mice, suggesting that necroptosis is rather irrelevant for CRC development." (PMID 36077828, 2022).
coronary artery disease (3 papers, 2020 to 2025). "In one cross-sectional study, the plasma levels of the necroptotic marker RIPK3 were correlated with the severity of coronary artery disease (i.e. low in stable coronary disease, higher in unstable angina, and highest in MI)." (PMID 33836761, 2021). "Cardiovascular burden, defined as the coexistence of ischemic heart disease, congestive heart failure, and hypertension, is closely linked with both AKI and mortality and may influence cell signaling pathways in which TRAIL and RIPK3 are involved." (PMID 41009652, 2025). "In the two last decades, the pathologic role of necroptosis in coronary artery disease has come to light, and the contributions of RIPK1 and RIPK3 to acute MI have emerged." (PMID 33142926, 2020).
depression (3 papers, 2021 to 2025). "Taken together, these results suggested that H2S is dependent on inhibiting hippocampal necroptosis to attenuate the hippocampal neuroinflammation and depressive-like behaviors in CUMS-exposed rats and identified RIPK3 as a potential therapeutic target for depression." (PMID 41208865, 2025). "We raised another hypothesis that fluoxetine may inhibit RIPK1/RIPK3/MLKL-induced necroptosis of astrocytes in MDD to protect astrocyte injury and to reduce proinflammatory cytokines (such as IL-6 and TNF-α) induced by depression disorder." (PMID 36686688, 2022). "In the current study, we found a reduced number of astrocytes and elevated levels of necroptosis kinases, including RIPK1/p-RIPK1, RIPK3/p-RIPK3, and MLKL/p-MLKL, in hippocampal astrocytes of depression-like behavior mice." (PMID 36686688, 2022). "In order to explore the possible mechanism of necroptosis in the mouse model of depression, the expressions of RIPK1, RIPK3, MLKL, p-MLKL were detected by western blot assay." (PMID 34867405, 2021). "To further confirm whether inhibiting necroptosis is capable of ameliorating depression, we will explore whether GSK872, a RIPK3 inhibitor, ameliorates the depressive-like behavior of CUMS-exposed rats." (PMID 41208865, 2025).
fungal infection (3 papers, 2017 to 2022). "The residual activation we observed in ZBP1/RIPK3-deficient BMDMs in this study suggests that there could be additional pathways or PANoptosome components such as RIPK1 that are functioning during fungal infection." (PMID 33109609, 2020). "WT BMDMs released a significant amount of IL-18 after fungal infection, whereas the Casp1/11–/–Ripk3–/–Casp8–/– BMDMs released significantly less." (PMID 33109609, 2020). "Collectively, these findings establish a novel link between these PCD components and immune response to cryptococcal challenge, demonstrating the crucial importance of FADD and RIPK3 in maintaining immune homeostasis during invasive fungal infection." (PMID 28919893, 2017). "Collectively, these data indicated that C. neoformans infection affected apoptotic rates of certain leukocyte subsets, but only the joint FADD/RIPK3 deletion led to detectable alterations in the APF in these leukocyte subsets during fungal infection." (PMID 28919893, 2017). "Together, these findings document that responses “designed” to be protective in fungal infections can become highly detrimental to the host, and our data demonstrate such detrimental outcomes following RIPK3 and FADD deletion." (PMID 28919893, 2017). "While PCD pathway components were shown to be important regulators of the immune responses, the role of FADD and RIPK3 in host defenses against fungal infection remained unknown up to this point." (PMID 28919893, 2017). "This novel link between the protective effect of FADD and RIPK3 in antifungal defense and sustenance of immune homeostasis may be important for the development of novel immunomodulatory therapies against invasive fungal infections." (PMID 28919893, 2017). "Collectively, our study shows that RIPK3 and FADD factors are crucial elements of regulatory network that allows protecting the host from pathological effects of inflammation while supporting clearance of the invasive fungal infection." (PMID 28919893, 2017). "Thus, while future studies are needed to provide definitive answers, our data favor the hypothesis that RIPK3 and FADD can induce immunoregulatory effects during fungal infection in a manner independent of their role in PCD responses, but chiefly by regulating cytokine responses." (PMID 28919893, 2017).
Glucose intolerance (3 papers, 2016 to 2025). Glucose intolerance (GI) can be defined as dysglycemia that comprises both prediabetes and diabetes. "Additionally, Mlkl deficiency improved insulin sensitivity, whereas Ripk3 deficiency exacerbated glucose intolerance in aged mice." (PMID 39930289, 2025). "Although the reasons for the reduced lifespan in Ripk3−/− mice are unclear, increased glucose intolerance with age and pre-diabetic or diabetic conditions are associated with reduced lifespan in humans." (PMID 39930289, 2025). "Collectively, these findings provide evidence that RIPK3 prevents glucose intolerance in obese mice by inhibiting Caspase-8-dependent adipocyte apoptosis in WAT." (PMID 27323669, 2016). "Here, the authors show that genetic ablation of Ripk3 results in adipocyte apoptosis and white adipose tissue inflammation in obese mice, which promotes glucose intolerance." (PMID 27323669, 2016). "Genetic inactivation of Ripk3 promotes increased Caspase-8-dependent adipocyte apoptosis and WAT inflammation, associated with impaired insulin signalling in WAT as the basis for glucose intolerance." (PMID 27323669, 2016). "Our data in obese mice suggest that RIPK3 in adipose tissue maintains homeostasis and dampens inflammation by inhibiting Caspase-8-dependent apoptosis of adipocytes, thereby preventing glucose intolerance." (PMID 27323669, 2016). "On the basis of these findings, we next tested whether additional deletion of Caspase-8 in hepatocytes (Caspase-8LPC-KO) could also rescue KO mice from glucose intolerance (RIPK3−/−/Caspase-8LPC-KO)." (PMID 27323669, 2016). "Interestingly, WT→RIPK3−/− mice after 16 weeks of CD-HFD presented with a significantly stronger glucose intolerance and higher insulin levels than RIPK3−/−→WT animals." (PMID 27323669, 2016). "Thus, glucose intolerance and altered fuel utilization may negatively impact lifespan of Ripk3−/− mice." (PMID 39930289, 2025). "However, our present findings in Ripk3-deficient mice underline that activation of apoptosis in WAT adipocytes is linked with detrimental unwanted metabolic side effects including inflammation and glucose intolerance." (PMID 27323669, 2016). "Thus, genetic ablation of Ripk3 promotes the development of glucose intolerance in obese mice." (PMID 27323669, 2016). "The findings suggest that targeting Mlkl or Ripk3 could provide therapeutic benefits in reducing age-related liver inflammation and pathology; however, Mlkl is a better candidate based on the adverse effects of Ripk3 deletion on glucose intolerance and lifespan." (PMID 39930289, 2025).
gout (3 papers, 2017 to 2018). A condition characterized by painful swelling of the joints, which is caused by deposition of urate crystals. "On the other hand, neutrophil necroptosis induced by MSU crystals was shown to be reduced by either necrostatin-1 treatment or by silencing the Ripk3 gene in experimental mouse gouty arthritis models." (PMID 29371616, 2018). "Thus, RIPK1, RIPK3, and MLKL might serve as molecular targets for gout therapy." (PMID 29371616, 2018).
HCMV infection (3 papers, 2021 to 2025). "We found HCMV infection significantly increased the ratio of pRIPK3 to RIPK3, which was reduced by the presence of iTLR3 to levels comparable to control uninfected monocytes." (PMID 41190811, 2025). "As we previously reported, HCMV infection increased both protein abundance and phosphorylation of RIPK3, an essential component of the necrosome." (PMID 41190811, 2025). "HCMV infection rapidly stimulates autophagy to block the execution of necroptosis by preventing activated RIPK3 from phosphorylating MLKL." (PMID 41190811, 2025). "Taken together, by restoring RIPK3 expression, we established a cell culture model in which necroptotic signaling can be studied in the context of HCMV infection." (PMID 38400065, 2024). "For example, TLR3-induced necroptosis in fibroblasts and endothelial cells did not require RIPK1 but involved both RIPK3 and MLKL, whilst necroptosis due to cytomegalovirus infection was RIPK1-independent but involved RIPK3 activity." (PMID 33925729, 2021). "We previously reported that the inhibition of procaspase-8 cleavage during HCMV infection of monocytes is necessary for RIPK3 phosphorylation, although the co-stimulatory signal required to activate RIPK3 remains unknown." (PMID 41190811, 2025). "Thus, we first examined the localization of pRIPK3 and RIPK3 following HCMV infection by subcellular fractionation." (PMID 41190811, 2025). "Thus, TLR3 appears to respond to HCMV infection by increasing both RIPK3 protein abundance and phosphorylation levels in order to initiate the necroptotic pathway within infected monocytes." (PMID 41190811, 2025). "Regardless, TLR3 is critical to the early activation of RIPK3 following HCMV infection, yet it remains unclear how TLR3 signaling is triggered following infection." (PMID 41190811, 2025). "Additionally, UV-HCMV infection alone increased RIPK3 levels and stimulated phosphorylation, indicating viral entry is sufficient to activate RIPK3." (PMID 41190811, 2025). "As expected, HCMV infection stimulated the cytoplasmic abundance of pRIPK3 and RIPK3." (PMID 41190811, 2025). "To investigate necroptotic cell death in the context of HCMV infection, we first analyzed two HCMV permissive cell types for RIPK3 expression." (PMID 38400065, 2024). "cFLIPL-mediated inhibition of caspase-8 and the simultaneous activation of TLR3, but not TNFR1 or TLR4, is required for RIPK3 activation following HCMV infection of monocytes." (PMID 41190811, 2025).
ischemia reperfusion injury (3 papers, 2018 to 2021). Adverse functional, metabolic, or structural changes in ischemic tissues resulting from the restoration of blood flow to the tissue (reperfusion), including swelling; hemorrhage; necrosis; and damage from free radicals. "Here, we sought to further examine the activation of necroptosis in kidney ischemia-reperfusion injury (IRI) and from TNFα-induced severe inflammatory response syndrome (SIRS), two models of RIPK3-dependent injury." (PMID 29500402, 2018).
Lewis Lung Carcinoma (3 papers, 2017 to 2024). "To explore whether re-expression of RIPK3 might enhance anti-tumor immune surveillance, we first attempted to restore expression of endogenous RIPK3 in Lewis Lung Carcinoma cells expressing chicken ovalbumin (LLC-OVA) using the DNA methyltransferase inhibitor 5-AZA-dC." (PMID 38196632, 2023). "FADD deficiency did not sensitize these cells to necroptosis because neither A549 nor murine Lewis lung carcinoma (3LL) cells express detectable levels of RIPK3." (PMID 28212753, 2017).
listeria infection (3 papers, 2020 to 2024). "RIPK1 immunoprecipitates from livers of both mouse strains contained RIPK3 with an increased amount in OTUB1LPC-KO mice indicating that OTUB1-deficiency increases necroptosis during listeriosis." (PMID 33712742, 2021). "However, at this time point, bacterial burden in spleen was significantly higher in RIPK3–/–, Casp-1/11–/–, and Casp-1/11–/–/RIPK3–/– double deficient in comparison to WT mice, suggesting that both RIPK3 and Casp-1/11 are important to control the early phase of listeria infection." (PMID 32328060, 2020). "For instance, Listeria monocytogenes infection induced activation of RIPK3-MLKL signaling axis in human cells, and the active MLKL directly bound to the bacteria and inhibited the bacterial replication." (PMID 38292869, 2024).
lung disease (3 papers, 2020 to 2022). "Pulmonary diseases in which necroptosis/RIPK3 plays a role are thought to include COPD, idiopathic pulmonary fibrosis, and asthma." (PMID 36224345, 2022). "Quantification of vessel diameter illustrated that while the size of the aorta of Ripk3+/+→WT mice with ALI gradually increased compared to mice with no lung disease, the dimension of aorta of Ripk3−/−→WT mice with or without ALI remained comparable to baseline levels for 28 days." (PMID 32855420, 2020).
malignant mesothelioma (3 papers, 2022 to 2025). A malignant neoplasm of the pleura or peritoneum, arising from mesothelial cells. "DNA methylation of RIPK3 impaired necroptosis and led to chemoresistance and poorer prognosis in malignant mesothelioma." (PMID 37095524, 2023). "For example, ectopic activation of RIPK3 was suggested to act as a cancer suppressor to inhibit malignant mesothelioma progression by inducing necrotic apoptosis." (PMID 37095524, 2023). "RIPK3 may act as a tumor suppressor to inhibit malignant progression of malignant mesothelioma through induction of necrotic apoptosis, whereas RIPK3 DNA epigenetic silencing of methylation impairs necroptosis and leads to chemoresistance as well as poorer prognosis in malignant mesothelioma." (PMID 35958626, 2022).
metastatic melanoma (3 papers, 2015 to 2024). A melanoma that has spread from its primary site to another anatomic site. "B-Raf(V600E) inhibitors, such as Dabrafenib, are an important anticancer drug class for metastatic melanoma therapy, that seem to inhibit the RIPK3 enzymatic activity in vitro, through their ATP-competitive binding to the enzyme." (PMID 33050394, 2020).
osteoporosis (3 papers, 2020 to 2022). A condition of reduced bone mass, with decreased cortical thickness and a decrease in the number and size of the trabeculae of cancellous bone (but normal chemical composition), resulting in increased fracture incidence. "proved, from the standpoint of genetic gene variations, that RIPK3 is one of the genes identified in the research as associated with osteoporosis." (PMID 36339402, 2022). "An osteoporosis-relevant eQTL association was identified in this study for the eBMD GWAS variant rs3212240, which was found to be significantly associated with expression of the RIPK3 gene, a member of the receptor-interacting protein (RIP) family of serine/threonine protein kinases." (PMID 32216834, 2020). "are examining the expression of RIPK1 and RIPK3 in GIOP rats after glucocorticoid (dexamethasone) injection to induce osteoporosis pharmacologically." (PMID 36339402, 2022). "Mice lacking one of the genes of interest, the apoptosis/necroptosis gene RIPK3, show disturbed bone micro-architecture and increased osteoclast number, highlighting a new biological pathway relevant to osteoporosis." (PMID 32216834, 2020). "Studies have found that excessive alcohol consumption leads to activation of RIPK1/RIPK3/MLKL signaling which increases necrotrophic apoptosis of osteoblasts and reduces osteogenic differentiation and bone formation in vivo and in vitro, leading to the development of osteoporosis." (PMID 35118075, 2021).
pancreatic adenocarcinoma (3 papers, 2020 to 2024). "The expression of RIPK1, RIPK3, and MLKL was also reported to be upregulated in pancreatic adenocarcinoma (PDA)." (PMID 31914150, 2020). "Conversely, in the cases of RIPK3 and FASLG, between the CNV mutation rates and the expression levels, showed a negative correlation in THYM and pancreatic adenocarcinoma (PAAD)." (PMID 37000317, 2023).
pneumonia (3 papers, 2022 to 2025). An acute, acute and chronic, or chronic inflammation focally or diffusely affecting the lung parenchyma, caused by an infection in one or both of the lungs (by bacteria, viruses, fungi, or mycoplasma.). "The KPn pneumonia model further corroborates that targeting the necroptosis pathway (via RIPK1/RIPK3 inhibitors) not only restores efferocytic capacity but also significantly improves disease outcomes." (PMID 40861493, 2025). "RIPK3 is considered a key regulator of inflammation and cell death, and significantly elevated RIPK3 protein concentrations have been detected in patients with S. pneumoniae pneumonia." (PMID 38933265, 2024).